FABP4 (fatty acid binding protein 4)
Diseases named in the same sentence as FABP4 in open-access papers (continued):
Sharing a sentence is not in itself a finding about the gene and the disease.
Hyperglycemia (24 papers, 2011 to 2025). An increased concentration of glucose in the blood. "In the present study, decreased of plasma FABP4 level was associated with hyperglycemia induced by STZ injection." (PMID 24593955, 2014). "Circulating FABP4 has been demonstrated to promote hyperglycemia and to stimulate hepatic glucose production by regulating expression of key gluconeogenic enzymes." (PMID 34676825, 2021). "Propionate was found to induce glycogenolysis and hyperglycaemia via the upregulation of glucagon and fatty acid-binding protein 4 (FABP4), thereby hindering the effects of insulin." (PMID 33062141, 2020). "A downstream mediator of VEGF/VEGFR2 in our study, FABP4 was found to be increased by metformin under hyperglycemia-CoCl2 at 12 h of CoCl2 enhancing cell survival and migration." (PMID 29351188, 2018). "Fatty acid binding protein 4 (FABP4) mRNA levels were downregulated at 12 h of CoCl2 in euglycemia (−1.6-fold, p = 2.4 × 10−2) and hyperglycemia (−1.6-fold, p = 2.9 × 10−2)." (PMID 29351188, 2018). "A candidate pathway for unconventional secretion has been highlighted in differentiated 3T3-L1 adipocytes with respect to the secretion of aP2 (FABP4) which contributes to increased liver glucose secretion and consequently, hyperglycemia and T2D." (PMID 28550272, 2018). "Conversely, the expression of FABP4 was significantly induced by adding metformin to HUVEC cultured under hyperglycemia-CoCl2 at 12 h of CoCl2 (1.6-fold, p = 2.53 × 10−2)." (PMID 29351188, 2018). "Correlations with measures of hyperglycemia, adiposity, lipids, blood pressure and inflammation were generally weaker, exceptions being FABP4 and ADM which correlated with body fat content (r = 0.75 and r = 0.69, respectively), and IL6 which correlated with CRP (r = 0.63) and WBC (r = 0.62)." (PMID 33279861, 2021). "In fact, glycogenolysis and subsequent hyperglycemia could be almost completely prevented when Fabp4 was either genetically deleted or pharmacologically neutralized, despite an intact increase in glucagon level." (PMID 34676825, 2021). "In this experimental study, we found that hyperglycemia in streptozotocin- induced diabetic rats was associated with higher plasma apoA-I and lower FABP4 levels than non-diabetic control rats." (PMID 24593955, 2014). "For example, fatty acid binding protein 4 (FABP4), produced by LSEC in response to hyperglycaemia, VEGF and hypoxia, is increased in NAFLD and HCC patients." (PMID 32982772, 2020). "Our microarray experiments demonstrated that metformin upregulated downstream targets in VEGFA pathway; MMP16, FABP4, ROCK1, TFPI2, CXCL-8, and LY96 under hyperglycemia-CoCl2, which play a part in cell migration." (PMID 29351188, 2018). "Therefore, metformin’s dual effect in hyperglycemia-chemical hypoxia is mediated by direct effect on VEGFR1/R2 leading to activation of cell migration through MMP16 and ROCK1 upregulation, and inhibition of apoptosis by increase in phospho-ERK1/2 and FABP4, components of VEGF signaling cascades." (PMID 29351188, 2018).
lung cancer (22 papers, 2014 to 2026). A malignant neoplasm involving the lung. "Mutations in the Src gene are common in lung cancer, and the release of Src’s inhibitory effect leads to an increase in FABP4 levels." (PMID 39744129, 2024). "For instance, Src inhibition has been linked to the induction of FABP4-mediated lipolysis via PPARγ activation, which contributes to the inhibition of lung cancer growth." (PMID 38921583, 2024). "FABP4 was selected in the workflow using an open-source database related to lung cancer, L-carnitine (PPAR pathway), and AF." (PMID 39458176, 2024). "Tissue FABP4 is a factor for poor prognosis in lung cancer; the high gene expression of FABP4 in tissue predicts survival in patients with squamous cell carcinoma." (PMID 39458176, 2024). "Fatty acid-binding protein 4 (FABP4) was selected as a candidate biomarker from 1472, 63, and 26 proteins related to lung cancer, L-carnitine, and AF, respectively." (PMID 39458176, 2024). "The FABP4 expression in the adjacent normal tissue is reported to be high in various malignant tumors, including lung cancer, compared with that in tumor tissue." (PMID 39458176, 2024). "Further studies with larger sample sizes are necessary to confirm the utility of FABP4 as a predictor of POAF in lung cancer surgery." (PMID 39458176, 2024). "The results showed that the expression of MMP9 and MMP12 in lung cancer tissues was higher than that in normal tissues adjacent to cancer, and the expression of CD36 and FABP4 in lung cancer tissues was lower than that in normal tissues adjacent to cancer." (PMID 37978381, 2023). "In contrast, Src inhibition decreases PPARγ expression and subsequently reduces FABP4, which blocks cell survival in lung cancer cells." (PMID 35216267, 2022). "In lung cancer, it was determined that the expression of FABP4 can be induced by the transcriptional activity of PPARγ, mediating lipolysis and tumor growth suppression." (PMID 31803141, 2019). "In the TCGA cohort, the AUC values ​​of CBLC, FABP4, GDF10, and LTBP4 genes were 0.982, 0.997, 0.980, and 0.983, respectively, indicating that these genes have a high diagnostic efficiency in distinguishing lung cancer samples from normal control groups." (PMID 40766337, 2025). "In an independent external sequencing sample cohort, these genes also performed impressively, with the AUC value for CBLC at 0.800, while the AUC values for FABP4, GDF10, and LTBP4 all reached 1.000, further validating their potential as diagnostic markers for lung cancer." (PMID 40766337, 2025). "Furthermore, in paired samples from lung cancer patients, the upregulation of FABP4 has also been confirmed to correlate with better patient prognosis." (PMID 39744129, 2024). "Inhibition of FABP4 expression increases lipid droplet catabolism, which may help to reduce tumour growth in lung cancer patients by increasing endogenous ROS levels." (PMID 36532833, 2022). "Furthermore, pharmacological stimulation of PPARγ leads to an elevation in the production of fatty acid binding protein 4 (FABP4), which is followed by an increase in the amount of reactive oxygen species in lung cancer cells." (PMID 38933330, 2024). "Additionally, circ_SCN8A enhances the expression of fatty acid-binding protein 4 (ACSL4) by binding to miR-1290, promoting lung cancer cell proliferation and migration, and inhibiting ferroptosis." (PMID 39139574, 2024). "However, the expression difference of FABP4 and OCIAD2 genes in H1299 lung cancer cells was insignificant, but both showed a trend of increase." (PMID 37409245, 2023). "In addition, the chemical activation of PPARγ increases fatty acid binding protein 4 (FABP4) expression, which is accompanied by increased levels of intracellular reactive oxygen species in lung cancer cells." (PMID 34775964, 2021).
lung cancer (continued). "Whereas, other proteins, such as LPCAT2 that is highly expressed in inflammatory cells, BPIFA3 that is highly expressed in lung cancer, PPIA that activates NFkB pathway, and FABP4 that has pro-angiogenic role, were downregulated in SBP1 overexpression xenograft tumors." (PMID 25974208, 2015). "Similarly, in lung cancer or osteosarcoma lung metastases, RTM-TAMs are characterized by high levels of MARCO, scavenger receptor (SIGLEC1 (CD169)), and fatty acid-binding protein 4 (FABP4) expression, which is also characteristic of alveolar macrophages." (PMID 39941714, 2025). "For the genes in module m63, A2M was in limited and extended lung cancer patients compared to a nonsmoker and smoker control population, FABP4 was down-regulated in lung adenocarcinoma, and CASP1 affected the single-nucleotide polymorphisms, increasing the cancers risk." (PMID 24643254, 2014).
Stroke (21 papers, 2011 to 2025). Sudden impairment of blood flow to a part of the brain due to occlusion or rupture of an artery to the brain. "Fabp4 is a marker of stroke risk, a prognostic indicator of stroke outcome and is a pro-angiogenic factor expressed in vascular endothelial cells." (PMID 32300198, 2020). "For each 1 ng/ml increment of FABP4 level in serum, the risk of stroke recurrence would be elevated by 12% in unadjusted model (with the OR of 1.12 [95% CI 1.06–1.17], P<0.001) and 8% in adjusted model (1.08 [1.02–1.14], P=0.006)." (PMID 30969942, 2019). "The mechanism of the positive association between FABP4 level and stroke recurrence risk was uncertain." (PMID 30969942, 2019). "Previous studies had showed that circulating levels of FABP4 were associated with stroke risk, severity and functional outcome in patients with acute ischemic stroke." (PMID 30969942, 2019). "The serum FABP4 levels were in 206 Han Chinese nondiabetic patients with ischemic stroke, and the associations between serum FABP4 levels and stroke recurrence in 3-month follow-up were explored." (PMID 30969942, 2019). "As a continuous variable, the unadjusted and adjusted risk of stroke recurrence would be increased by 12% (OR=1.12 [95% CI 1.06–1.17], P<0.001) and 8% (1.08 [1.02–1.14], P=0.006) for every 1 ng/ml increment of FABP4." (PMID 30969942, 2019). "Circulating biomarkers which constitute the typical lipid patient profile (LDL-C, TC, triglyceride, Ox-LDL, Lp-PLA2), inflammatory biomarkers such as hs-CRP, TNF-α, IL-6, adipokines (adiponectin, leptin, FABP4) and homocysteine are related to the high risk of future stroke." (PMID 34829489, 2021). "Furthermore, elevated serum levels of FABP4 (>22.8 ng/ml) were correlated with stroke recurrence, in which the risk was elevated by 272% (OR=3.72 [95% CI 1.74–7.92], P<0.001) and 129% (2.29 [1.31–5.11], P=0.003), respectively." (PMID 30969942, 2019). "In the multivariate analysis, the date showed that for each 1 ng/ml increase of FABP4, the association between FABP4 and stroke recurrence was stronger among patients who defined as obese (OR= 1.14, 95%CI: 1.09-1.22; P<0.001) versus non-obese (OR=1.06, 95%CI: 1.02-1.14; P=0.016)." (PMID 30969942, 2019). "High FABP4 levels had been related to risk and severity in patient with stroke." (PMID 30969942, 2019). "We could assess the real relationship between the FABP4 and stroke recurrence to exclude the effects caused by metabolic abnormalities." (PMID 30969942, 2019). "It aimed to investigate the associations of serum FABP4 levels with early stroke recurrence." (PMID 30969942, 2019). "The associations between FABP4 and stroke had been proposed in recently studies." (PMID 30969942, 2019). "Hence, the true association between FABP4 and stroke recurrence might be caused by those adipokines confounds." (PMID 30969942, 2019). "However, future studies in larger stroke populations with differing etiology, reflecting the general stroke population, are needed to evaluate if FABP4 could be a biomarker for clinical risk stratification in patients with acute ischemic stroke." (PMID 22174896, 2011). "Thus, it is tempting to hypothesize that the association of FABP4 with adverse outcome in stroke patients may reflect its ability to mirror upstreams pathways (e.g., lipid interaction with macrophages) that are only partly reflected by other biomarkers." (PMID 22174896, 2011). "We detected a significant reduction in PPARγ DNA-binding activity in the brain tissue and mRNA levels of BBB junctional proteins and PPARγ-targeting gene CD36 and FABP4 in cerebral microvasculature at 24 h after stroke." (PMID 32012810, 2020). "Because it makes critical effects at multiple stages of stroke development, FABP4 will be worthy of further research as a possible therapeutic target." (PMID 30969942, 2019). "The discriminating capacity of FABP4 for predicting stroke recurrence was evaluated with AUC (0.73, 95% CI 0.64–0.82)." (PMID 30969942, 2019).
Stroke (continued). "Logistic regression model for serum levels of FABP4 quartiles using stroke recurrence as the dependent variables‡." (PMID 30969942, 2019). "Median of serum FABP4 levels in patients with stroke recurrence was 22.6 (IQR, 17.9-31.6) ng/mL, which was higher than those of without stroke recurrence [16.9, (IQR, 11.8-21.4) ng/mL]." (PMID 30969942, 2019). "The distribution of stroke recurrence across the FABP4 quartiles was ranged from 5.8% (Q1) to 34.0% (Q4)." (PMID 30969942, 2019). "In another study, plasma levels of FABP4 were also evaluated in relation to symptoms in 59 patients with carotid plaques and 202 having suffered from stroke of another origin." (PMID 25960621, 2015). "To further examine the relation of FABP4 to stroke, we examined determinants of FABP4 and the ability of baseline levels of FABP4 in plasma to predict long-term prognosis in 202 patients with acute ischemic stroke." (PMID 22174896, 2011). "For all cause mortality, multivariate analysis indicated that the interaction term between the top tertiles of stroke severity and FABP4 was preferred over these factors alone with a similar HR as in univariate analysis (HR 3.27 95%CI = 1.46−7.34; P = 0.004)." (PMID 22174896, 2011). "In addition, a study by Tu and colleagues showed that FABP4 is a prognostic biomarker in stroke patients." (PMID 34987673, 2021). "The authors also showed that elevated FABP4 levels were associated with death, nonlethal myocardial infarction, and nonfatal stroke." (PMID 32887447, 2020). "Above results indicated the potential role of FABP4 in stroke." (PMID 30969942, 2019). "The correlation of FABP4 levels with stroke subtypes was also tested." (PMID 30969942, 2019). "The results indicated that increased FABP4 level in serum was related to higher risk of early stroke recurrence in the future, independent of baseline variables." (PMID 30969942, 2019). "A significantly higher discriminating capacity was still observed for FABP4 to predict stroke recurrence (AUC, 0.75; 95% CI, 0.70–0.81), compared to Hs-CRP (AUC 0.70; 95% CI, 0.62–0.76; P=0.009), HCY (AUC 0.71; 95% CI, 0.63–0.78; P=0.01) and NIHSS score (AUC 0.77; 95% CI, 0.70–0.83; P=0.09)." (PMID 30969942, 2019). "The risk of stroke recurrence can be predicted by elevated FABP4 levels in serum of nondiabetic patients with first-ever ischemic stroke." (PMID 30969942, 2019). "Also, correlation analyses should be interpreted with caution, and further mechanistic studies as well as studies in larger stroke populations are needed to elucidate the role of FABP4 in atherosclerotic disorders." (PMID 22174896, 2011). "In addition, other biomarkers such as serum fatty acid binding protein 4 (FABP4), serum CXCL12 levels, interleukin-37, and cystatin C have been reported to be associated with stroke recurrence." (PMID 37051146, 2023). "However, in the multivariate analysis, serum FABP4 still was a positive risk factor for stroke recurrence independent from BMI in non-diabetic patients." (PMID 30969942, 2019). "Thus, the impact of those factors on stroke recurrence in relation to the serum FABP4 remains unclear." (PMID 30969942, 2019). "FABP4 levels were higher in patients with carotid atherosclerosis, both systemically and within the atherosclerotic lesion, than in patients having suffered from a stroke from another origin, with particularly high mRNA levels in carotid plaques from patients with the most recent symptoms." (PMID 25960621, 2015). "There were very few deaths within the first 30 days, further suggesting that FABP4 levels at baseline may reflect the severity of the underlying atherosclerotic process rather than the severity of the index stroke." (PMID 22174896, 2011). "There were very few deaths within the first 30 days (n = 7), indicating that FABP4 levels at baseline may reflect the severity of the underlying atherosclerotic process rather than the severity of the index stroke (i.e., SSS)." (PMID 22174896, 2011).
Stroke (continued). "The rFGF21 administration given 6 h after stroke eliminated this reduction (263.8% increase in CD36 and 199.6% increase in FABP4), which reflected the change of cerebrovascular PPARγ activity." (PMID 32012810, 2020). "Our results showed there were significant reductions of both PPARγ downstream genes after stroke (there was 96.8% reduction in CD36 mRNA level and 73% reduction in FABP4 mRNA level) in db/db mice compared to those in db/+ mice." (PMID 32012810, 2020). "The Area under the curve (AUC) of serum FABP4 and NIH Stroke Scale (NIHSS) score for predicting stroke recurrence was 0.73 (95% CI: 0.64–0.82) and 0.72 (95% CI: 0.64–0.81), presenting no discriminating capacity (P=0.45)." (PMID 30969942, 2019). "However, associations between serum FABP4 levels and stroke recurrence had not been explored." (PMID 30969942, 2019). "A serum FABP4 level was identified as the prognostic molecule in T2DM and stroke patients." (PMID 36670935, 2022). "Our study has been the first study showed that nondiabetic stroke patients with elevated levels of FABP4 were more likely suffered from stroke recurrence in the future." (PMID 30969942, 2019). "Without serial testing of FABP4 levels, we yielded no data regarding the change of FABP4 levels in those nondiabetic stroke patients." (PMID 30969942, 2019). "Furthermore, secretion of adipokines, including omentin-1, retinol-binding protein 4 (RBP4), fatty acid–binding protein 4 (FABP4) was altered in adipose tissue dysfunction and might play role in the prognosis of stroke." (PMID 32771014, 2020). "Thus, we hypothesized that FABP4 level in serum was related to the prevalence of stroke recurrence in nondiabetic ischemic stroke." (PMID 30969942, 2019).
gestational diabetes mellitus (19 papers, 2018 to 2025). "Recent studies have investigated the circulating adipocyte fatty acid binding protein (FABP4), nesfatin-1, and osteocalcin (OC) concentrations in women diagnosed with gestational diabetes mellitus (GDM), but the findings prove to be conflicting." (PMID 32861247, 2020). "Throughout pregnancy, FABP4 affects maternal–fetal interface homeostasis by affecting both glycolipid metabolism and immune tolerance, leading to adverse pregnancy outcomes, including miscarriage, gestational obesity, gestational diabetes, and preeclampsia." (PMID 37628833, 2023). "Maternal circulating FABP4 level is increased in gestational diabetes mellitus." (PMID 34676825, 2021). "To study the dynamics in FABP4 serum levels in mothers and offspring, we first tested FABP4 serum levels in normoglycemic pregnant women (control) and women with gestational diabetes mellitus (GDM)." (PMID 34676825, 2021). "The expression of chemerin, fatty acid binding protein 4 (FABP4), and the inflammatory factors IL-6 and TNF-α are increased in the peripheral blood of gestational diabetes patients." (PMID 37964253, 2023). "This was also observed with glucagon, where FABP4 promotes hepatic glucose production irrespective of insulin, particularly in women with gestational diabetes mellitus (GDM)." (PMID 38731797, 2024).
bladder cancer (18 papers, 2008 to 2025). "The PD-1/PD-L1 immunotherapy based on bladder cancer further demonstrated that high levels of FABP4, CDR2L, and FSTL3 expression were associated with a poor response to immunotherapy, confirming the applicability of the associated immune dysregulation across various tissues and diseases." (PMID 40595026, 2025). "In addition, loss of FABP4 expression is associated with the progression of bladder cancer." (PMID 36060264, 2022). "FABP4 intimately participates in bladder cancer cell progression, and Bid is well-known for the pro-apoptotic protein." (PMID 36362994, 2022). "Among the main repressed genes in bladder cancer, there are fatty acid binding protein 4 (FABP4) and fibroblast growth factor binding protein 1 (HBP17), RGS4, tissue inhibitor of metalloproteinase 3 (TIMP3), WNT5b, URB, and collagen type VIII, alpha 1 (COL8A1)." (PMID 34835969, 2021). "In addition, in other tumors, such as bladder cancer, FABP4 was reported to be expressed in tumor cells and is related to the pathology." (PMID 24732569, 2014).